IFNG (interferon gamma)
Diseases named in the same sentence as IFNG in open-access papers (continued):
Sharing a sentence is not in itself a finding about the gene and the disease.
melanoma (continued). "To investigate whether the distinction also exists between normal and melanoma tissue, we tested the tetrad of IL2RA, IL2R, IFNG, and IL7R transcriptional expression between normal samples and melanoma samples with RT‐PCR, and observe the same expression pattern as expected." (PMID 34159752, 2021). "Moreover, IFNγ signatures (CXCL10, CXCL9, IDO1, IFNG, and STAT1) and myeloid lineage phenotypic and functional markers (CD14, CD163, CD33, and CD68) were also significantly increased in melanoma patients with high ETV7." (PMID 33424867, 2020). "In a melanoma mouse model consisting in B16.SIY melanoma cells subcutaneously transplanted into immunocompetent 6-week old wild-type C57BL/6 mice, TL from the tumor microenvironment express very high levels of PD-L1 and indoleamine-2,3-dioxygenase, both induced by IFNγ production by CD8+ TLs." (PMID 33381116, 2020). "It appears that the melanoma intrinsic FTO pathway is not only critical for melanoma malignant traits and tumorigenicity in immunocompromised hosts, but also crucial for promoting resistance to IFNγ-induced killing in vitro and anti-PD-1 blockade in immunocompetent hosts in vivo." (PMID 31239444, 2019). "However, FTO knockdown in melanoma cells did not affect the number of IFNγ-producing CD4+ or CD8+ TILs s." (PMID 31239444, 2019). "Control CEA-CAR T cell IFNγ production was absent in response to T2.A1 cells but could be found upon co-culture with A375M melanoma cells." (PMID 31195686, 2019). "Although it is still not clear whether incomplete IFNγ stimulation in melanoma cells has significant impact on patient responses to immunotherapy, it is evident that this pathway is important for response to PD-1 blockade." (PMID 29977240, 2018). "Importantly, 5/7 melanoma cell lines with no IFNγ-mediated PD-L1 induction showed no cell cycle profile changes after treatment with IFNγ." (PMID 29977240, 2018). "IFNγ could induce expression of suppressor‐of‐cytokine‐2 (SOCS2) protein, a conserved program transcript, which is expressed by mononuclear phagocytes infiltrating primary melanoma." (PMID 30039553, 2018). "This may be due to IFNγ concentration effects, as previous reports have shown that 50 U/ml IFNγ was sufficient to arrest UVM cells, whereas concentrations exceeding 1,000 U/ml IFNγ were required to inhibit the growth of the cutaneous A375 melanoma cells." (PMID 29977240, 2018). "Interestingly, 72.3% of these γδ T cells from regressed melanoma specimens express IFNγ in this mixed culture of tumor and TILs without additional stimulation." (PMID 28424760, 2017). "Importantly, our mRNA-based microarray and NanoString screens revealed that frequently used normalization genes are not stably expressed in melanoma cells exposed to melanoma-specific CTLs or their cytokines (IFNγ/TNFα)." (PMID 27625650, 2016). "On the other hand, CEACAM1 expression modulates melanoma cell escape from immunologic attacks; when melanoma cells and tumor-infiltrating lymphocytes are coincubated in vitro, surviving melanoma cells increase CEACAM1 expression, which is dependent on constant presence of interferon gamma." (PMID 27642217, 2016). "Importantly, however, these data do not rule out the existence of melanomas constitutively expressing HLA-DR in the absence of IFNγ stimulation, as is observed in a significant number of melanoma cell line models." (PMID 26822383, 2016). "In addition, we identify five genes (ALG12, GUSB, RPLP0, KRBA2, and ADAT2) that are stably expressed in melanoma cells independent of the presence of T cells or the T cell-derived cytokines IFNγ and TNFα." (PMID 27625650, 2016). "Treatment of melanoma cells with IFNγ did not influence their response to TRAIL." (PMID 25428727, 2014). "Still, we did not observe sensitization of melanoma cells to TRAIL in the presence of IFNγ." (PMID 25428727, 2014).
melanoma (continued). "Basal and interferon-alpha (IFN-α) or interferon-gamma (IFN-γ)-induced expression of SOCS1 and SOCS3 proteins was evaluated by immunoblot analysis in a panel of n = 10 metastatic human melanoma cell lines, in human embryonic melanocytes (HEM), and radial or vertical growth phase melanoma cells." (PMID 20398276, 2010). "These upregulated genes are consistent with an antigenic IFNγ-responsive cell state with anti-apoptotic features, mirroring our in vitro observations of CTL-tolerant persisters and suggesting that persisters may constitute a subset of antigen presentation melanoma cells in human tumors." (PMID 40166148, 2025). "In addition to well-established IFNγ target genes such as CD274, IRF1, and B2M, three members of the PARP family—PARP9, −12 and −14—were consistently upregulated in all cell models as well as in IFNGhigh patient melanoma (comparing top 15% by IFNG expression to lowest 15% in the TCGA SKCM dataset)." (PMID 37752135, 2023). "Thus, the increased frequencies of IFNγ-producing Tregs or CD4 Teffs, and granzyme Bhigh CD8 Teffs in TILs by anti-PD-1 and anti-CD80 treatment may all have contributed to the melanoma regression, suggesting a potential combination therapy for melanoma with PD-1 and CD80 Abs." (PMID 35449134, 2022). "Melanoma cell lines grown in vitro do not have TILs present, and yet some melanoma cell lines constitutively express high PD-L1 levels, while other melanoma cell lines express low baseline levels of PD-L1, but the latter subgroup can be induced to express higher PD-L1 levels with IFNγ stimulation." (PMID 34503064, 2021). "Firstly, the concentration of the endogenous IFNγ may be too low to stimulate the IFNγR; secondly, IFNγR is functionally inactive, as demonstrated in renal cell carcinomas; and, finally, STAT-1 lacks TGCT, as shown in pul-monary carcinoma and malignant melanoma cells." (PMID 12942126, 2003). "In our study, DMF reversed melanoma resistance to NKmK, reducing MHC II expression without affecting upstream IFNγ targets (USF1, IRF1, IRF2)." (PMID 41078003, 2025). "While the overall counts of CD3+, CD4+, and CD8+ T cells remained stable (data not shown), a marked increase in IFNγ expression was detected in circulating CD4+ cells and CD8+ T cells in patients with STS and melanoma 4 weeks after CPMV treatment." (PMID 40386779, 2025). "The interferon-gamma (IFN-γ) signature has been identified as potentially prognostic and predictive in stage III melanoma, but its use is not standard in clinical practice." (PMID 41517320, 2025). "Four other melanoma cell lines do not increase PD-L1 mRNA expression following MITF knockdown and IFNγ treatment." (PMID 39736644, 2024). "Most secreted factors (TNFα, GM-CSF, G-CSF, PDGF-BB, CCL5, CCL11, IL-3, IL-6) were not induced by exogenous IFNγ in our panel of melanoma cells, confirming the complex inflammatory signaling profile of de-differentiated PD1 PROGs with intrinsic IFNγ signaling." (PMID 36934113, 2023). "IFNγ and TNF were not effective alone and only induced death of IFN-responsive HCmel12 Ciita-KO melanoma cells when used in combination." (PMID 37316667, 2023). "All seven PRE-melanoma cell lines had intact IFNγ signaling, accumulated cell surface MHC-I and MHC-II molecules, and did not display intrinsic IFNγ activity." (PMID 36934113, 2023). "The percentages of polyfunctional (IFNγ+TNFα+) total MAIT cells and CD4+ MAIT cells were reduced in melanoma patients compared to HD, while no changes in the production of these cytokines by CD8+ or double‐negative (CD4−CD8−, DN) MAIT cells were observed." (PMID 35028137, 2022). "Genetic alterations in antigen presentation (B2M, HLA-A) and IFNγ signaling (IFNGR, STAT1 and JAK1/2) in non-responding melanoma patients are uncommon, and not restricted to non-responding patients." (PMID 32312968, 2020).
melanoma (continued). "A predominant expression of IDO1 in the tumor endothelial cell fraction was also noted in HCmel12 melanomas, but the level of IDO1 and of intratumoral IFNγ were not significantly increased by anti-CD40 therapy in this model." (PMID 32231867, 2020). "Here, we report that the main response to agonostic CD40 mAb therapy in murine melanoma tumor endothelial cells is not due to engagement of CD40 on endothelial cells, but secondary to IFNγ-secretion by activated cytotoxic T-cells." (PMID 32231867, 2020). "In pooled analyses with TCLs/TCLs + IFNγ and FTDs (n = 186), the mean proportion of tumor-reactive CD8+ TILs of melanoma samples, regardless of previous anti-PD-1 therapy, far surpassed other cohorts (p < 0.001)." (PMID 33198174, 2020). "The CSPG4-specific CAR-T cells recognized the CSPG4-positive melanoma cell line A375M and responded with the production of IL-2, TNF, and IFNγ, while the CSPG4-negative target cell line 293T was not recognized." (PMID 31426437, 2019). "Although there appear to be altered killing and IFNγ production by NK cells, chronic engagement of NKG2D did not appear to alter B16-F10 melanoma tumor growth following subcutaneous injection in vivo." (PMID 31396217, 2019). "We first set up a co-culture system using the melanoma cell line Mel 103, which has low PDL1 cell surface expression independent of exogenous IFNγ treatment, as well as the same cell line with stable overexpression of PDL1." (PMID 28325288, 2017). "Melanoma cell lines were incubated with PR-924 in presence/absence of IFNγ for 72 h and the ability of NY-ESO-1 specific HLA-Cw3 restricted T-lymphocytes to recognize or kill melanoma cells lines was assessed." (PMID 26885372, 2016). "Collectively, these results indicate that Ad-Ii-GP-induced reduction of melanoma metastasis is mediated by CD8 T cells and that IFNγ, but not perforin, inhibits tumor cell growth." (PMID 24498205, 2014). "Pretreatment with IFNγ did not, but addition of MA3 peptide did, enhance killing of the MZ2-MEL43 melanoma cells by MA3/DP4 TCR T cells." (PMID 22400038, 2012). "We performed HPLC-MS measurements of the IDO1 substrate tryptophan and its immunosuppressive product kynurenine in conditioned media of human melanoma cells (WM35) treated with either HPI-1, vismodegib or the IDO1-specific inhibitor epacadostat with or without IFNγ." (PMID 39962447, 2025). "Leveraging The Cancer Genome Atlas (TCGA) datasets, we investigated NR4A1 expression in melanoma patients and identified a negative correlation between NR4A1 and genes involved in the antitumor immune responses, including IFNγ (interferon γ), GZMB (granzyme B), and PRF1 (perforin)." (PMID 38334978, 2024). "Indeed, in obese mice where IFNγ expression by CD8+ TIL is compromised, MHC-I and MHC-II expression remained low on Gp100+ melanoma cells but elevated in lean mice, and this was not the result of differences in IFNγ-receptor expression." (PMID 38565540, 2024). "In addition, assessment of lymph nodes with or without melanoma metastases has shown a lower CD4/CD8 ratio and decreasing IFNγ levels with increasing number of nodal metastases." (PMID 35336796, 2022). "Evidence suggests a transcriptional regulation of the antigen presentation machinery, as genetic alterations in antigen presentation (B2M, HLA-A) and IFNγ signaling (IFNGR, STAT1 and JAK1/2) remain infrequent in melanomas and are not restricted to non-responding patients." (PMID 35432344, 2022). "When only responses to TCLs/TCLs + IFNγ were considered, responses were increased in MM PD-1 res samples compared to RCC (p < 0.05), in both melanoma cohorts (regardless of previous anti-PD-1 treatment) compared to OC (p < 0.001) and in SAR compared to OC (p < 0.01) (n = 135)." (PMID 33198174, 2020).
melanoma (continued). "We recently observed that cells in the invasive melanoma cell line, B16-BL6, highly express IDO2 whereas the less invasive melanoma cell line, B16F10, had limited expression of IDO2 in the absence of interferon-gamma (IFN-γ) induction." (PMID 27058624, 2016). "These responding CD8+ T-cells produced high amounts of IFNγ and could kill DNBS-modified autologous melanoma cells; cytolytic activity to unmodified cells was not examined." (PMID 24949488, 2014).
viral infection (1,354 papers, 2004 to 2026). "IFNγ in the lungs exerts a protective effect during viral infection and lower levels of IFNγ in the lungs are associated with more severe disease." (PMID 40636105, 2025). "For example, it is accepted that deficiencies in type I/III signaling confer susceptibility to viral infections, whereas deficiencies in IFNG signaling are associated with mycobacterial disease." (PMID 35217532, 2022). "Exogenous interferon gamma (IFNγ) delivery to compensate its deficiency in susceptible to virus infection." (PMID 33791293, 2021). "IFNγ is traditionally associated to protection against viral infections such as dengue, herpes and measles." (PMID 33410731, 2021). "The network centred on SLFN5 was enriched with genes linked to interferon gamma upregulation and viral infection." (PMID 31953380, 2020). "This case further confirms an enhanced risk for viral disease in IFNγR-deficient patients and a role of interferon gamma for human antiviral defense." (PMID 33051801, 2020). "Pathway and gene-ontology clustering identified the Interferon gamma signalling pathway as the most relevant amongst all significant molecules, and viral infections as the most likely cause of all down-stream events observed." (PMID 29618802, 2018). "In turn, KIR expression on NK cells is critical for robust IFNγ production, a potential mechanism underlying both control of viral infection and suppression of tumor growth after HSCT." (PMID 27980216, 2017). "Interferon gamma (IFNγ) has been associated with AA and type I IFNs (alpha and beta) are well documented to cause bone marrow aplasia during viral infection." (PMID 27621733, 2016). "Virus-specific T cells produce copious amounts of IFNγ and TNFα that in turn affect hematopoiesis; besides, chronic (latent or active) viral infections can induce chronic inflammation, associated with increased risk of developing BM pathology." (PMID 27695457, 2016). "This strain is also highly susceptible to LT relative to all other inbred strains, and it has been shown to have a deficient interferon gamma response during viral infection." (PMID 23506131, 2013). "The C1.7+/CD28+ subsets of CD8+ T cells is associated with higher cytotoxic activity and interferon-gamma production, and this subset is thought to control viral infections by mediating cytolytic activity against viral infected cells." (PMID 17521440, 2007). "Similarly, IFNγ has been demonstrated to cause insulin resistance in muscle cells, promoting pancreatic insulin secretion during viral infections." (PMID 39768214, 2024). "For example, some authors associated IFNG haplotypes with the susceptibility to virus infection, such as hepatitis B virus, T-lymphotropic virus type 1 infection, or tuberculosis, as well as bacterial infections such as brucellosis, or parasitic infections such as malaria." (PMID 36759910, 2023). "Similarly, upregulation of IFNγ signaling in microglia after viral infection promoted synapse loss and cognitive deficits in mice." (PMID 37428916, 2023). "Since BIRC genes may play roles in cell fate following viral infection, we tested whether the viral infection-associated cytokine, IFNG, could enhance BIRC2 and/or BIRC3 expression." (PMID 37289679, 2023). "Adaptative immune responses may influence the risk of viral infections in newborns as their CD4+ T cells have delayed synthesis of IFNγ and IL-2 in presence of viral infections." (PMID 36482106, 2022). "Gene set enrichment analysis confirmed the most significant positive enrichment for GO gene sets linked to virus infection such as “GO response to virus” as well as gene sets linked to IFN signaling such as “GO responses to type I interferon” as well as “GO response to interferon gamma”." (PMID 33544398, 2021). "Patients with asthma may have deficient IFNγ response leading to prolonged and more severe viral infections, deficient IFNγ response has also been linked to Th2 type immune reaction." (PMID 32292784, 2020).
viral infection (continued). "Interferons are secreted to defend against viral infections, and in patients with asthma, deficient IFNγ response may lead to prolonged and more severe viral infections." (PMID 32292784, 2020). "Although other inflammatory mediators may contribute to IFNγ production, we did not observe any correlation with IL-12, IL-15, or other molecules previously reported to be associated with IFNγ and/or viral infections such as IP-10, MIG, I-TAC, MCP-1, RANTES." (PMID 28830544, 2017). "Interestingly, activated NK cells and CD8+ T cells, known for production of IFNγ in response to Tp, are typically associated with degranulation in response to viral infection and tumor cells but Tp is an extracellular pathogen." (PMID 29051759, 2017). "Hence, we provide the first evidence for of a unique mechanism of IFNγ production by NK cells which regulates susceptibility to viral infection." (PMID 25473962, 2014). "Furthermore, viral infections may cause insulin resistance because of the downregulation of insulin receptor expression in skeletal muscle due to virus‐induced interferon gamma." (PMID 35478440, 2022). "Both cigarette smoke and nicotine have been shown to inhibit pulmonary T cell responses, including secretion of IFNγ, and enhance susceptibility to virus infection, which suggests that exposure to nicotine, such as in E-cigs, may exhibit immunosuppressive effects." (PMID 25651083, 2015). "CXCL9 and CXCL10 were identified among DEGs and are host response factors to viral infection downstream of IFNγ." (PMID 41516395, 2026). "Children with allergic rhinitis and asthma demonstrate decreased interferon-gamma production, increasing vulnerability to viral infections (particularly rhinovirus) and bacterial infections such as Mycoplasma pneumoniae." (PMID 40564746, 2025). "In contrast to ubiquitin, FAT10 expression is specifically induced by the pro-inflammatory cytokines TNF and IFNγ, which are predominantly secreted by CTLs during viral infection." (PMID 40821782, 2025). "Viral diseases and other intracellular pathogens are best controlled by type 1 responses characterized by cytokines such as type 1 IFNs, IFNγ, TNFα, and IL-2 along with antibody isotypes IgG2a/c (depending on mouse strain)." (PMID 40872809, 2025). "In future, broad tests with other pro‐inflammatory stimuli, such as cytokines (IFNγ, TNFα, and IL‐1β) and virus infection, are suggested." (PMID 39455284, 2025). "This distinction is attributed to the production of interferon-gamma (IFN-γ) during viral infections, which inhibits PCT synthesis." (PMID 40217585, 2025). "Siglec-1 expression on myeloid cells is induced by IFNγ and is thought to play an important role in the initiation of an immune response to viral infections." (PMID 40636105, 2025). "We monitored RBD-S1-specific T cell reactivities against a pool of eleven non-overlapping peptides (“PEPwtRBD”) to determine inter- and intra-individual variations in IFNγ release induced by vaccination or viral infection." (PMID 41282134, 2025). "These cultured MPs are, therefore, far from being able to facilitate a functional TL profile compatible with the control of viral infection, which would involve the secretion of IFNγ, IL2 and TNFα." (PMID 40181981, 2025). "IFNα DE genes were strongly enriched for GO terms relating to response to viral infections and regulation of innate immune responses, whereas IFNγ DE genes were enriched for regulation of the innate immune response and the humoral immune response." (PMID 41503139, 2025). "Many antiviral proteins, induced by IFNγ, help in countering numerous viral infections at several stages, such as in viral entry, un-coating, blocking viral translation or virion assembly." (PMID 40264756, 2025). "The dual and opposing role of IFNγ is reflected not only in viral infection but in cancer development as well." (PMID 40264756, 2025).